INS (insulin)
Diseases named in the same sentence as INS in open-access papers (continued):
Sharing a sentence is not in itself a finding about the gene and the disease.
diabetes (continued). "Linear regression for associations of TMAO and related metabolites with insulin and glucose levels and Gutt ISI, and proportional hazards regression for associations with diabetes." (PMID 34448864, 2021). "Generally, the body weights of the rats in the T2DM-genipin + insulin group increased in diabetes to the highest value compared with the T2DM-insulin and T2DM-genipin groups." (PMID 33446235, 2021). "Patients with crural index IV in insulin-treated diabetes mellitus (p = 0.001) and non-insulin-treated diabetes mellitus (p = 0.013) had higher mortality after revascularization." (PMID 33225841, 2021). "Our work highlights the critical role of insulin signaling in nociceptive sensory neurons in the regulation of diabetes-induced nociceptive hypersensitivities." (PMID 34549177, 2021). "After the injection of the bolus of glucose and the insulin, plasma glucose levels were significantly higher in diabetics than in control rats at all the time points tested." (PMID 34202017, 2021). "This post-authorization study was conducted to evaluate the safety of insulin degludec/insulin aspart (IDegAsp) in adult patients with diabetes mellitus (DM) during routine clinical care under a real-world setting in India." (PMID 35076540, 2021). "The individualized metabolic surgery (IMS) scoring system was based on independent predictors (number of diabetes medications, insulin use, duration of diabetes, and glycemic control) to guide procedure selection based on long-term (>5 years) diabetes control." (PMID 34378729, 2021). "Diabetes is nothing but a condition in which our body cannot satisfy enough insulin or when the body is totally immune to insulin in general." (PMID 33692919, 2021). "Diabetes mellitus (DM) is a metabolic disorder with chronic hyperglycemia featured by metabolic outcomes owing to insufficient insulin secretion and/or insulin effect defect." (PMID 34133443, 2021). "Type 1 diabetes accounts for about 5–10% of all diabetics, which is due to β-cell dysfunction, decreased insulin release, and decreased circulating insulin level." (PMID 33937267, 2021). "Diabetes complications were present in 38.7% of the persons with diabetes and 60.7% of them were treated with insulin." (PMID 35136475, 2021). "This meta-analysis is novel work as there were only a few studies conducted in the Asian population to compare the safety and efficacy of currently available long-acting insulin (insulin degludec and glargine) in type 2 diabetes mellitus patients." (PMID 34345540, 2021). "Our top 500 sites included genes that were significantly enriched for insulin signaling pathway and type 2 diabetes mellitus pathway." (PMID 33499918, 2021). "Current diabetes treatments include insulin and a number of oral antidiabetic drugs with severe adverse effects; thus, it remains a challenge to manage diabetes without any side effects." (PMID 33920728, 2021). "Across four primary studies of adults with insulin-treated diabetes, the Diabetes Fear of Injecting and Self-testing Questionnaire (D-FISQ) yielded estimates of needle fear between 0.2–43% (section 1c)." (PMID 34111207, 2021). "Continuous glucose monitoring systems are increasingly being adopted as an alternative to self-monitoring of blood glucose (SMBG) by persons with diabetes mellitus receiving insulin therapy." (PMID 33836819, 2021). "In obesity and diabetes, adipose tissue expands by increasing the size of adipocytes (hypertrophy), which damages insulin sensitivity." (PMID 33671428, 2021). "Selective sodium-glucose cotransporter 2 inhibitors provide an insulin-independent mechanism to improve blood glucose levels and are approved for the treatment of type 2 diabetes mellitus." (PMID 34823419, 2021). "A recent study of twelve-month treatment with GLP-1RA, SGLT-2i, and their combination showed greater improvement in vascular markers and effective cardiac cycles than insulin treatment in type 2 diabetes mellitus." (PMID 33397395, 2021).
diabetes (continued). "Type 2 diabetes mellitus (T2DM) is a metabolic disorder of complex aetiology characterised by a deficiency, and/or dysfunction of endogenous insulin and glucagon production." (PMID 34081167, 2021). "Because of this, diabetes interferes with spermatogenesis by interfering with insulin’s regulating influence on serum FSH levels." (PMID 35054403, 2021). "The primary etiologic classification was suggested for the first time already in 1951, in a study in which the discrimination between insulin-dependent and non-insulin-dependent diabetes mellitus was stated for the first time." (PMID 34299114, 2021). "High-density lipoproteins provide protection against the damaging effects of glucolipotoxicity in beta cells, a factor which sustains insulin secretion and staves off onset of type 2 diabetes mellitus." (PMID 33805674, 2021). "In another investigation, it has been reported that thymoquinone significantly prevented male Wistar experimental rats from streptozotocin‐induced diabetes via lowering blood glucose level, and increasing insulin levels, and catalase and GSH activities." (PMID 33747489, 2021). "The established risk factors for fractures in patients with T2DM are the following: longstanding diabetes mellitus, presence of diabetes mellitus complications and especially diabetic retinopathy, history of insulin use, and poor glycemic control." (PMID 34007765, 2021). "Family history of diabetes also influences insulin resistance and insulin secretion, in the Chinese population." (PMID 33490287, 2021). "The diabetes was treated with a continuous subcutaneous insulin infusion pump and continuous glucose monitoring." (PMID 34093443, 2021). "The primary treatment available for diabetes at present is exogenous insulin injections which besides being painful, requires regular blood glucose monitoring to avoid over dosage and development of hypoglycaemia." (PMID 34869218, 2021). "Metformin should be withdrawn to avoid lactic acidosis in all patients with severe infections and insulin therapy should be started for patients with uncontrolled diabetes mellitus." (PMID 33025384, 2021). "Type I diabetes is caused by autoimmune-mediated beta-cell destruction, and the current treatment regimen for diabetes relies on the administration of exogenous insulin by frequent injections." (PMID 34287337, 2021). "Many substances are thought to be involved in the imbalanced growth of the fetus in diabetes; amongst them are insulin, glucose, leptin, adiponectin, ghrelin, and some growth factors." (PMID 33803995, 2021). "Beneficial effects of insulin administration, prevention of acute lung injury, adaptation to previous oxidant stress and nutritional intake in obese patients with diabetes were also proposed as protective against sepsis." (PMID 33973089, 2021). "Highly functioning FoxO1 triggers hyperglycemia as well as dyslipidemia, which are the features of diabetes and diabetic problems under insulin-resistant circumstances." (PMID 33804729, 2021). "Initially we discussed the molecular targets in diabetes by considering proteins involved in the metabolism and uptake of glucose, proteins that control insulin secretion and proteins involved in pancreatic β cell development." (PMID 34827690, 2021). "Congenital Generalized Lipodystrophy (CGL) patients generally have poorly controlled diabetes and require extremely high doses of insulin." (PMID 34130736, 2021). "In patients with diabetes, glucose homeostasis is dysregulated due to impaired insulin secretion and activity." (PMID 34213618, 2021). "Diabetes mellitus (DM) is a common metabolic disorder characterized by chronic hyperglycemia due to defective insulin secretion and/or utilization, which has been considered an enormous global health concern." (PMID 34349833, 2021). "Although insulin transcription is severely reduced in 1GG2GG mice, the degree of diabetes is mild, probably due to the remaining capacity of the pancreas." (PMID 34645928, 2021).
diabetes (continued). "Complementary to these sensors, diabetes management can reach a higher dimension, by actively monitoring blood glucose in diabetic patients and deliver, when necessary, insulin through in-body insulin pump actuators." (PMID 34696099, 2021). "Insulin resistance leads to diabetes mainly because insulin resistance affects the distribution of glucose in muscle and fat, and weakens insulin to inhibit glucose output in the liver." (PMID 34733558, 2021). "In an important study, a diabetic mouse transplanted with ESCs-derived insulin-secreting cells lowered the glucose level, however, resulted in teratoma formation, which limits its clinical potential in addressing diabetes and related complication." (PMID 34805412, 2021). "The translation of nutrition guidelines into easy practical advice is especially important for individuals with diabetes who are required to have advanced skills of counting carbohydrate intake depending on their insulin dosage and reading nutrition labels." (PMID 33805161, 2021). "Diabetes was more prevalent, haemoglobin A1C concentrations were larger, and insulin was used more frequently in black compared to other African patients." (PMID 33680512, 2021). "Cytokines play a crucial role in the development of diabetes, orchestrating the recruitment and action of immune cells, to not only destroy insulin-producing cells but also preserve them." (PMID 33604389, 2021). "Various studies have shown that phytochemicals are efficient agents in controlling diabetes via the control of glucose absorption, b-cell regeneration, insulin-releasing activity, as well as oxidation and inflammation." (PMID 33435282, 2021). "A total of 100,650 insulin-using people with diabetes met the study criteria, including 11,826 (11.7%) with T1DM and 88,824 (88.3%) with T2DM." (PMID 34238287, 2021). "Further, interaction of diabetes duration with insulin use: 1.03 [1.01, 1.07] was also a significant predictor of HTN among DM patients." (PMID 34424924, 2021). "“Monitoring helps control all other parts of the treatment: insulin, diet and exercise” (grandmother of a girl, 3 years 9 months with diabetes)." (PMID 33807277, 2021). "Top words included very explicit indicators of diabetes and related management tools including diabetes, #diabetes, and insulin." (PMID 34652277, 2021). "The first purification of insulin, from the cow pancreas, was performed by the Canadian biochemist James Collip and was used to treat the first human patient with diabetes, Leonard Thompson, in 1922." (PMID 34717951, 2021). "This included restaurants providing carbohydrate content information to facilitate insulin dosing and the sense of togetherness when an individual saw other patients with diabetes taking injections." (PMID 33496671, 2021). "For other comorbidities, a large-scale prospective study suggested that hypertension and insulin-required diabetes mellitus were independent predictors of unanticipated early postoperative intubation." (PMID 33435881, 2021). "The modest increase in insulin concentrations produced by Lepvv is corroborated by a modest reduction in hyperglycemia resulting from diabetes." (PMID 34947993, 2021). "Diabetes presents in varying forms—type 1, type 2, and gestational—and disease development is attributed to insufficient production or use of insulin in the body leaving an excess of glucose in the bloodstream to be used as energy." (PMID 34463627, 2021). "For the management of T2DM as well as pre-diabetes, improving insulin sensitivity is a crucial target." (PMID 35056941, 2021). "Adjusted for age, sex, medical history of diabetes, insulin-treated diabetes, myocardial infarction, underwent PCI/CABG, renal failure, stroke, heart failure, and COPD." (PMID 33981731, 2021). "As patients with diabetes have problems with regulating their glucose levels, we expect that the glucose and insulin lowering effects will be more pronounced in patients with diabetes." (PMID 34393698, 2021).
diabetes (continued). "Diabetes unfolds when the pancreatic beta cells fail to secrete enough insulin to meet physiological demand, resulting in abnormally high blood glucose levels." (PMID 33828531, 2021). "Knowledge gaps in any of these four mechanisms governing glucagon and insulin physiology will severely limit the development of diabetes models." (PMID 35002748, 2021). "While there are various kinds of drugs for type 2 diabetes mellitus at present, in this review article, we focus on metformin which is an insulin sensitizer and is often used as a first-choice drug worldwide." (PMID 33807522, 2021). "p.Lys68Gln carriers had a higher BMI, lower insulin secretion, worse diabetes control, and an increased urine albumin/creatinine ratio than p.Arg252His carriers." (PMID 34193236, 2021). "Thus, the American Diabetes Association and the Endocrine Society workgroup on hypoglycemia and diabetes emphasized that clinicians and educators need to assess the risk of hypoglycemia at every visit with patients treated with insulin and insulin secretagogues." (PMID 34946320, 2021). "In fact, in people with diabetes who routinely self-administer subcutaneous insulin injections, the skin disinfection rate was only 16% in Spain and 30% in Italy, and no major problems have been reported." (PMID 33418557, 2021). "Bariatric surgery improves both insulin sensitivity and secretion and can induce diabetes remission." (PMID 34453049, 2021). "Previous clinical studies have also reported greater satisfaction in patients with diabetes receiving treatment with insulin analogues compared with human insulin." (PMID 33905628, 2021). "Kamalden at al. have already described that in the early stages of diabetes, insulin production promotes the activation of hsa-miR-15a-5p expression, stimulating β cells." (PMID 33670401, 2021). "Further studies are needed to completely understand the precise molecular interactions between these factors that result, initially, in decreased insulin sensitivity, then in overt diabetes." (PMID 34444964, 2021). "The nomogram for score calculation is based on the four predictors of long-term remission, i.e., the number of diabetes medications, duration of diabetes, insulin use, and glycemic control (HbA1c <7%)." (PMID 34842637, 2021). "Poor knowledge of diabetes and insulin therapy, including storage conditions, is a factor for poor glycemic control." (PMID 34136581, 2021). "The CPE-E342Q mice exhibited poor prohormone processing as exemplified by decreased serum levels of insulin and elevated levels of proinsulin, leading to high circulating glucose and diabetes." (PMID 33414376, 2021). "According to the medication treatment, all the patients were divided as non-diabetes group, metformin group and insulin group." (PMID 33976288, 2021). "Blood pressure, BMI, total cholesterol, fasting triglycerides, fasting glucose and fasting insulin, as well as diabetes were significantly higher in the abnormal ECG group." (PMID 33957929, 2021). "Its role as a link between AD and diabetes mellitus has been proposed, due to its double degrading action on Aβ and insulin." (PMID 34944723, 2021). "Tandem's t:slim X2 insulin pump with Control-IQ technology offers a significant advancement in diabetes care." (PMID 32846114, 2021). "Children followed by Diabetes Prediction in Skåne (DiPiS) study experienced decreased HbA1C up to 24 months after the diagnosis against similar daily insulin dose requirements." (PMID 33794915, 2021). "These internal and external factors that influence the attitudes of patients toward insulin therapy can produce a complex “Psychological Insulin Resistance,” which ultimately can worsen diabetes." (PMID 34458301, 2021). "Improving diabetic pilgrims' knowledge of diabetes management, including insulin storage, will be beneficial during the pilgrimage and beyond." (PMID 34136581, 2021). "Impaired insulin secretion is thought to precede decreased beta cell mass in the progression of diabetes." (PMID 34843575, 2021).
diabetes (continued). "In that study, we established that diabetes-like conditions and disrupted insulin signaling result in prolonged thermal nociceptive hypersensitivity after tissue injury." (PMID 34549177, 2021). "The recommendations for the treatment of type 1 diabetes mellitus in Portugal propose different insulin therapeutic regimens, which incorporate the scientific evidence available for insulin therapy." (PMID 33627117, 2021). "TZD (troglitazone, rosiglitazone, and pioglitazone) are insulin-sensitizing compounds used to treat diabetes." (PMID 33926085, 2021). "Along these lines, Cx36 gap junction coupling and its modulation are increasingly recognized as vital components in normal islet function and potentially viable targets to help restore insulin secretion in diabetes." (PMID 34359828, 2021). "Several researches have demonstrated that KD can reduce glucose and insulin concentration in obese, insulin resistant individuals and diabetics." (PMID 33530512, 2021). "We used the k-means approach to perform clustering analyses using BMI, age at onset of diabetes, HbA1c, insulin secretion (HOMA2-B), and insulin resistance (HOMA2-IR) indices and glutamic acid decarboxylase antibodies (GADA) levels." (PMID 34276762, 2021). "Patients commonly have multiple comorbidities and behavioral challenges, such as a patient with obesity and diabetes who would benefit from adherence to statins and insulin, as well as better diet and weight management." (PMID 34605920, 2021). "Ghrelin is known to decrease as insulin levels rise in both rodents and humans, is correlated positively with insulin sensitivity, and has shown promise as a therapeutic target for diabetes." (PMID 33716966, 2021). "DKA typically occurs in patients with established diabetes mellitus who underwent insulin omission or inappropriate management of intercurrent illness or in patients with new-onset diabetes." (PMID 34044824, 2021). "This reflects the growing recognition of the role and value of long-acting insulin analogues in the management of patients with diabetes mellitus across Europe coupled with their increasing promotion." (PMID 34676266, 2021). "About 25 individuals reported using a second diabetes medication besides insulin, with the majority of them using either metformin or a sodium-glucose transport protein 2 (SGLT2) inhibitor." (PMID 34501920, 2021). "Male sex, insulin-treated diabetes, chronic kidney disease, and independency for activities of daily living are predictors of unexpected death." (PMID 33670462, 2021). "Diabetes mellitus (DM) is a collection of metabolic syndromes represented by hyperglycemia, inadequate insulin synthesis, and improper responses to insulin." (PMID 34037093, 2021). "In most patients with diabetes, the insulin-dependent pathway is affected by insulin resistance, but the insulin-independent pathway is not damaged and appears to maintain a normal function." (PMID 34645204, 2021). "For those who had diabetes, blood sugar monitoring and insulin injection also were the main behaviors to perform: “Basically, I use the glucometer to test the blood sugar every day." (PMID 34603098, 2021). "Type 1 Diabetes (T1D) is a chronic condition that requires checking blood glucose levels multiple times a day, multiple insulin injections daily, and/or use of durable medical equipment that provides the person with diabetes with insulin." (PMID 36994327, 2021). "This manuscript reports the Brazilian Diabetes Society Position Statement for insulin adjustments based on trend arrows observed in continuous glucose monitoring systems." (PMID 33390180, 2021). "The potential action of L. sativum and F. carica was comparable to that of the insulin reference medication used to treat diabetes." (PMID 34970629, 2021).